WNT3A (Wnt family member 3A)
Description:
Ligand for members of the frizzled family of seven transmembrane receptors (Probable). Functions in the canonical Wnt signaling pathway that results in activation of transcription factors of the TCF/LEF family. Required for normal embryonic mesoderm development and formation of caudal somites. Required for normal morphogenesis of the developing neural tube (By similarity). Mediates self-renewal of the stem cells at the bottom on intestinal crypts (in vitro).
Tractability: Small molecule: a structure with a bound ligand is known; a high-quality ligand is known. Antibody: UniProt places it where antibodies can reach, with high confidence; its Gene Ontology location is reachable by antibodies, with high confidence; UniProt predicts a signal peptide or a membrane-spanning region. PROTAC: a small molecule that binds it is known.
Target class: Secreted protein
Chemical probes: CCT251545 (high quality)
Gene: Protein-coding gene on chromosome 1 (228,006,924 to 228,061,271, forward strand). Ensembl gene ENSG00000154342.
Subcellular location: Secreted, extracellular space, extracellular matrix; Secreted
Subcellular location (Human Protein Atlas): Vesicles; Predicted to be secreted
Pathways (Reactome):
Signal Transduction: Class B/2 (Secretin family receptors); Disassembly of the destruction complex and recruitment of AXIN to the membrane; Negative regulation of TCF-dependent signaling by WNT ligand antagonists; Regulation of FZD by ubiquitination; TCF dependent signaling in response to WNT; WNT ligand biogenesis and trafficking
Developmental Biology: Formation of paraxial mesoderm; Formation of the posterior neural plate; Specification of the neural plate border; Transcriptional and post-translational regulation of MITF-M expression and activity
Disease: Signaling by RNF43 mutants
Gene Ontology:
Molecular function: co-receptor binding; protein binding; receptor ligand activity; signaling receptor binding; cytokine activity; frizzled binding; identical protein binding; protein domain specific binding; transcription coactivator activity
Biological process: canonical Wnt signaling pathway; cardiac muscle cell fate commitment; heart development; positive regulation of canonical Wnt signaling pathway; positive regulation of cardiac muscle cell differentiation; positive regulation of dermatome development; positive regulation of gene expression; positive regulation of mesodermal cell fate specification; positive regulation of receptor internalization; positive regulation of transcription by RNA polymerase II; regulation of presynapse assembly; regulation of synapse organization; secondary palate development; cell fate commitment; cell proliferation in forebrain; cell proliferation in midbrain; cellular response to retinoic acid; COP9 signalosome assembly; midbrain dopaminergic neuron differentiation; negative regulation of neurogenesis; negative regulation of neuron projection development; neuron differentiation; positive regulation of DNA-templated transcription; presynapse assembly; synaptic vesicle recycling; and 13 more
Cellular component: extracellular region; glutamatergic synapse; Wnt-Frizzled-LRP5/6 complex; cell surface; early endosome membrane; endocytic vesicle membrane; endoplasmic reticulum lumen; extracellular exosome; Golgi lumen; plasma membrane; presynapse; synapse
Genetic constraint (gnomAD): Loss-of-function variants: 17 observed, 33.55 expected, observed/expected ratio (o/e) 0.51, 90% interval 0.35 to 0.76. The upper end of that interval is the gene's LOEUF score, 0.76, which puts it in group 3 of 6, group 1 being the genes least tolerant of losing a copy. Missense variants: 411 observed, 497.66 expected, observed/expected ratio (o/e) 0.83, 90% interval 0.76 to 0.9. Synonymous variants: 187 observed, 203.31 expected, observed/expected ratio (o/e) 0.92, 90% interval 0.82 to 1.04.
Homologues: Orthologues: chimpanzee WNT3A (100% identical), macaque WNT3A (99% identical), mouse Wnt3a (95% identical), rat Wnt3a (95% identical), pig WNT3A (95% identical), dog WNT3A (94% identical), guinea pig WNT3A (87% identical), zebrafish wnt3a (83% identical), rabbit WNT3A (70% identical), Drosophila melanogaster Wnt2 (43% identical), Drosophila melanogaster Wnt5 (42% identical), Caenorhabditis elegans cwn-2 (41% identical), and 3 more. Paralogues in human: WNT3 (84% identical), WNT4 (46% identical), WNT5B (46% identical), WNT5A (45% identical), WNT1 (45% identical), WNT2 (44% identical), WNT2B (43% identical), WNT7A (42% identical), WNT7B (42% identical), WNT6 (41% identical), WNT10A (40% identical), WNT16 (40% identical), and 6 more.
Diseases named in the same sentence as WNT3A in open-access papers:
WNT3A is named in the same sentence as 212 diseases in open-access papers, as found by Europe PMC text mining. Sharing a sentence is not in itself a finding about the gene and the disease. The quoted sentences say what the papers report.
breast cancer (75 papers, 2006 to 2025). A primary or metastatic malignant neoplasm involving the breast. "The M. buxifolia persuaded the upregulation of proapoptotic marker genes (Caspase-1, -3, -7 and -9) and the downregulation of the WNT pathway associated genes WNT-3a and β-catenin, which caused apoptotic cell death in human breast cancer cells." (PMID 36904007, 2023). "Using patient-derived cell samples from both ER+ve (n = 3) and ER-ve (n = 3) breast cancer and normal breast tissue (n = 3) we found that WNT3A caused a significant increase in MS only in the ER-ve sample." (PMID 23861811, 2013). "First, we measured the ability of WNT5a to inhibit canonical WNT3a activity and, second, to induce invasiveness of luminal A breast cancer cells in an in vitro, modified Boyden chamber assay." (PMID 40165582, 2025). "For example, Wnt3a secreted by breast cancer cells induces adipocyte dedifferentiation by activating the Wnt/β-catenin signaling pathway in adipocytes." (PMID 39719444, 2024). "This means that WNT3a massively antagonizes the breast cancer relevant mechanism of aromatase induction in BAFs, here experimentally mimicked by forskolin stimulation." (PMID 36902090, 2023). "In breast cancer, the appearance of adipocyte-derived fibroblasts is stimulated through the activation of the Wnt/β-catenin pathway in response to Wnt3a secreted by the tumor." (PMID 37481560, 2023). "The breast cancer‐derived 5a‐D‐Luc‐ZsGreen cells were transfected with Wnt1, Wnt3A, and Wnt5A expression vectors, producing stably highly expressing cells." (PMID 37840014, 2023). "Repression of Wnt3a/FOXM1/β-Catenin pathway is widely involved in the apoptotic impact of moracin D in breast cancer." (PMID 35799265, 2022). "The previous study has shown that Wnt3a/GSK3β/Slug/Snail axis controlled EMT programs while coordinately regulating BRCA1 expression in breast cancer." (PMID 33589588, 2021). "Intriguingly, both canonical and noncanonical Wnt signaling pathways are activated in tamoxifen-resistant breast cancer cells, and Wnt3a increases the resistance of EsR+ breast cancer cells to tamoxifen treatment." (PMID 33234169, 2020). "Ykt6 knockdown in human Hek293T cells caused intracellular accumulation of overexpressed Wnt3A-GFP and reduced endogenous Wnt5A secretion from SK-BR-3 breast cancer cells." (PMID 32611603, 2020). "Activation of the Wnt/β-catenin signaling pathway by overexpressing Wnt-3a or FMOD in MDA-MB-231 cells enhanced breast cancer cell migration and invasion." (PMID 31824307, 2019). "Previous studies have identified stromal fibroblasts as the stem cell niche responsible for the production of periostin, a component of the extracellular matrix, to recruit Wnt1 and Wnt3A and then activate Wnt signaling in breast cancer stem cells." (PMID 30999932, 2019). "Mesoderm development (Mesd), which binds directly to mature LRP5 and LRP6 on the cell surface and inhibits Wnt3a-induced Wnt signaling, decreases the growth of breast cancer tumors in vivo." (PMID 29854300, 2018). "The authors showed that the suppression of DKK-1 by statin and amino-bisphosphonates inhibited the ability of breast cancer cells to block WNT3A-induced production of alkaline phosphates and bone-protective osteoprotegerin in preosteoblastic C2C12 cells." (PMID 30420710, 2018). "SOSTDC1, a secreted regulator of both BMP and Wnt signalling pathways, is under expressed in breast cancer and can differentially affect signalling induced by Wnt3a, BMP-2 and BMP-7." (PMID 28733469, 2017). "In contrast, a recent study reported the upregulation of Lgr5 expression in MMTV-Wnt1 mammary tumor cells and in human breast cancer cell lines when incubated with Wnt3a." (PMID 27420097, 2016).
breast cancer (continued). "In 4T1 murine mammary cancer cells, WNT3a was found to restore the suppressed cell viability by quercetin." (PMID 27391060, 2016). "In line with our results, silencing of BMI-1 in breast cancer cells was shown to impair Wnt signalling via downregulation of Wnt ligands (e.g. Wnt3a) and upregulation of Wnt inhibitors including DKK1." (PMID 26935956, 2016). "Actually, we found that the CD44-positive subpopulation in primary breast cancer cells (KBr2, KBr3 and KBr4), showed higher levels of AurkA and wnt3a mRNAs as well as increased migratory ability, compared to CD44-negative cells." (PMID 27341528, 2016). "Wnt3a can increase mammosphere formation in ER-positive breast cancer cell lines; however, only ER-negative mammospheres are responsive to the ligand Wnt3a in patient-derived metastatic breast cancer samples." (PMID 26369691, 2015). "Kallistatin inhibits the Wnt3a-induced proliferation, migration, and invasion of breast cancer cells." (PMID 26369691, 2015). "Co-injecting Wnt3a-expressing human mammary fibroblasts with human breast cancer cell lines into mouse mammary fat pads accelerates tumor growth." (PMID 26369691, 2015). "Genes up-regulated in Wnt3a-stimulated cell lines were more strongly expressed in TNBC than in luminal A breast cancer samples." (PMID 25848952, 2015). "Deep-sea water treatment results in a concomitant decrease in mRNA levels of MMP-9, transforming growth factor-β (TGF-β), Wnt5a, and Wnt3a in human breast cancer MDA-MB-231 cells." (PMID 26369691, 2015). "Wnt3a expression is higher in most breast cancer cell lines than in normal human mammary epithelial cells, which is also true in oral squamous cell carcinoma compared with control nonmalignant tissues." (PMID 26369691, 2015). "To test the impact of Wnt on miR-29 in breast cancer cells, we treated T47D cells independently with Wnt3a or insulin and found a noticeable increase in levels of miR-29 a and b." (PMID 25174825, 2014). "To strengthen our finding, we have analysed p68 expression in various breast cancer cell lines under enhanced Wnt signaling by Wnt3a-CM treatment." (PMID 25499975, 2014). "Suppression of DKK-1 inhibited the ability of breast cancer cells to block WNT3A-induced production of alkaline phosphates and bone-protective osteoprotegerin in preosteoblastic C2C12 cells." (PMID 24528599, 2014). "We have discovered that junction plakoglobin (JUP) interacts with SOX4 in both the cytosol and the nucleus and the interaction between SOX4 and plakoglobin is significantly increased when prostate and breast cancer cells are stimulated with WNT3A." (PMID 22098624, 2011). "Furthermore, differential expression of the canonical Wnt ligand Wnt3a was correlated with decreased overall survival across all breast cancer subtypes." (PMID 37092550, 2023). "In breast cancer cells, there is overexpression of WNT3A, WNT4, WNT6, WNT8B, WNT9A and WNT10B." (PMID 35453754, 2022). "Specifically, WNT3A was reported in many cancer studies as a major participant in malignant cell invasion, including cancer types such as hepatocellular carcinoma, glioma, breast cancer, esophageal cancer, and colon cancer." (PMID 36555553, 2022). "Interestingly, interfering with the β-catenin-Bcl9/Bcl9L-Pygo chain of adapters only partially impaired the transcriptional response of mammary tumor cells to Wnt3a and TGFβ treatments." (PMID 34545187, 2021). "Interestingly, mammary fibroblasts engineered to secrete Wnt3A have been found to promote or inhibit tumour growth in xenografts derived from two different breast cancer patients." (PMID 31147591, 2019). "As for CN gain genes, WNT3A was a highly-expressed gene in ER+ breast cancer cell lines." (PMID 28415743, 2017). "Moreover, our study suggests AurkA/miR-128/Wnt3a axys as a druggable target to inhibit chemoresistance and recurrence in breast cancer." (PMID 27341528, 2016).
breast cancer (continued). "Moreover, Wnt3a promotes the proliferation of breast cancer MCF7 cells and increases the expression of high-mobility group A protein 1 to maintain the proliferation of gastric cancer cells." (PMID 26369691, 2015). "We show that zoledronic acid and atorvastatin, two clinically approved inhibitors of the mevalonate pathway, effectively inhibit the Wnt inhibitor DKK-1 in breast cancer cells and, thereby, prevent the inhibition of WNT3A-induced OPG production in osteoblasts in vitro." (PMID 24528599, 2014). "Furthermore in cell lines, the ligand Wnt3a increased whilst the inhibitor DKK1 reduced mammosphere formation with the greatest inhibitory effects observed in ER+ve breast cancer cell lines." (PMID 23861811, 2013). "Our results suggest that breast cancer-associated aromatase activity, and estrogen production, not only depend on activating factors from different sources, but also on the absence of inhibitory signaling molecules, such as WNT3a." (PMID 36902090, 2023). "Furthermore, NDR1 might function as a hub to modulate IL-6, TNF-α or Wnt3a induced activation of Notch1 signaling pathway and enrichment of breast cancer stem cells." (PMID 35508987, 2022). "Thus, we wanted to determine whether CS-E could interfere with Wnt3a-mediated receptor activation in breast cancer cells." (PMID 25090092, 2014). "However, addition of CS-E treatment to Wnt3a stimulation severely reduced nuclear beta-catenin expression levels, suggesting that CS-E, but not C4S, is a potent inhibitor of Wnt/beta-catenin signaling in breast cancer cells." (PMID 25090092, 2014). "During the research, it was discovered that a particular type of breast cancer cell, namely MDA-MB-231, exhibited a robust response to Wnt3a, a Wnt protein responsible for activating the canonical Wnt signaling pathway." (PMID 38260135, 2023). "Furthermore, we identified Wnt response elements in the breast cancer relevant aromatase promoter I.3/II region, and identified a switch in promoter occupancy from TCF-4 to a LEF-1 variant, which appears to be involved in the WNT3a induced suppression of aromatase in BAFs." (PMID 36902090, 2023). "In basal breast cancer cells, activation of WNT/β-catenin signalling by WNT3A represses IGFBP5; however, the mechanism has not been identified." (PMID 35048158, 2022). "They concluded that blockade of the Wnt3a/FOXM1/β-catenin axis and activation of GSK-3β is essential for inducing apoptosis in breast cancer cells." (PMID 35744950, 2022). "Taken together, our results indicated that TQ suppressed VM network formation and metastasis in breast cancer cell line MDA-MB-231 through modulating PI3K, Wnt3a, VE-cadherin pathways which are essential signaling in VM network formation." (PMID 33663486, 2021). "Studies have elucidated that hsa-miR-103 and hsa-miR-107 were involved in Wnt3a/β-catenin/ATF6 signaling pathway and were critical to the progression of colorectal cancer, Alzheimer's disease, breast cancer and cardiac function 33-36." (PMID 34093822, 2021). "b mRNA expression of WNT3A, WNT3, WNT5A, WNT5B, and WNT11 in five different breast cancer subtypes based on bc-GenExMiner v4.1 according to the Sørlie’s subtypes (****p < 0.0001; Red star: the former > the latter; Green Star: the former < the latter)." (PMID 31462314, 2019). "In breast cancer cells, SOSTDC1 modestly increases Wnt3a signalling, decreases BMP-7 signalling, whilst eliciting little effect on BMP-2-induced signalling." (PMID 28733469, 2017). "Niclosamide and silibinin inhibit LRP6 expression and phosphorylation, block Wnt3a-induced β-catenin accumulation, and inhibit Wnt/β-catenin signaling in HEK293 cells, prostate cancer PC-3 and DU145 cells, and breast cancer MDA-MB-231 and T-47D cells." (PMID 26369691, 2015). "Wnt target genes up-regulated in Wnt3a-stimulated HCC38 cells and their enrichment in human breast cancer samples." (PMID 25848952, 2015).